IL1B (interleukin 1 beta)
Diseases named in the same sentence as IL1B in open-access papers (continued):
Sharing a sentence is not in itself a finding about the gene and the disease.
Arthritis (656 papers, 2005 to 2026). Inflammation of a joint. "It has been reported that IL-1β is the most important cytokine in the development of pathogenic arthritis and has been linked to symptoms such as morning stiffness." (PMID 37259429, 2023). "IL-1β is the most crucial cytokine in the formation of pathogenic arthritis and has been connected to signs such as morning stiffness." (PMID 37111308, 2023). "SKG arthritis symmetrically affects joints and is associated with the elevation of key RA cytokines including IL‐6, IL‐1β, and TNF." (PMID 36890657, 2023). "Anti-inflammatory cytokine IL-10-deficient mice exhibit severe antigen-induced arthritis with the upregulated expression of IL-1β and NLRP3 in the synovium." (PMID 35628185, 2022). "Impairing macrophage glycolysis in RA is associated with inflammasome disassembly, decreased IL-1β production, and arthritis remission." (PMID 35844594, 2022). "Arthritis in KLF2 deficient animal model is dependent on IL-1β which in turn can be controlled by the NF-κβ pathway." (PMID 36466816, 2022). "In humans, severe CHIKV arthritis is associated with elevated serum cytokine/chemokine levels, such as IL-1β, IL-6, TNF-α, CXCL10, etc.." (PMID 36377866, 2022). "A recent study showed that TLR7 deficiency alleviated K/BxN serum-induced arthritis by imparing interferon regulatory factor 5 (IRF5) mediated IL-1β and IL-6 produced by macrophages and synovial fibroblasts, respectively." (PMID 34950033, 2021). "A recent study also showed that TLR7 deficiency led to K/BxN serum-induced arthritis reduction by imparing interferon regulatory factor 5 (IRF5) mediated IL-1β and IL-6 generation in macrophages and synovial fibroblasts, respectively." (PMID 34950033, 2021). "IL-1β, the most significant cytokine in pathogenic arthritis progression, has been reported to be correlated with disease behavior such as morning stiffness period." (PMID 33488761, 2021). "NFIL3 mutation can sensitise for arthritis development, in mice and humans, and rewires the innate immune system for IL-1β over-production." (PMID 30552177, 2019). "The potential contribution of this mutation to arthritis susceptibility was demonstrated through a preclinical model, where Nfil3-deficient mice upregulated IL-1β production, with more severe arthritis symptoms on disease induction." (PMID 30552177, 2019). "Recently, a treatment comprising IL-1β in combination with IL-17A reportedly enhanced the expression of genes associated with arthritis and cell migration in a monolayer culture of the human synovial sarcoma cell line." (PMID 31614911, 2019). "SATB2 expression levels were negatively associated with the levels of TNF-α both in OVX-induced bone loss and IL-1β-induced arthritis mice." (PMID 29435145, 2018). "In ovariectomy (OVX) -induced bone loss and IL-1β-induced arthritis mice models, we examined SATB2 and TNF-α expression levels by immunohistochemistry using the antibodies specific for TNF-α and SATB2." (PMID 29435145, 2018). "The pro-inflammatory and arthritis-associated cytokine IL-1β is a potent inducer of ADAMTS activity in chondrocytes." (PMID 29720262, 2018). "Accordingly, in the current study, the arthritis caused by CFA injection significantly increased the serum levels of IL-1β in the different days of study up to 21 days." (PMID 30719247, 2018). "We found that the SATB2 expression levels were negatively associated with the expression levels of TNF-α both in ovariectomy (OVX) -induced bone loss and IL-1β-induced arthritis animal models." (PMID 29435145, 2018). "Tryptase inhibition was effective in inhibiting some inflammatory parameters associated to mBSA/IL-1β-induced arthritis, notably late phase oedema formation and IL-6 production, but not neutrophil infiltration and joint degeneration." (PMID 28587618, 2017). "Neutrophil-derived proteases, including NE or cathepsins, have been implicated in caspase-1 independent pro-IL-1β processing in arthritis and Pseudomonas aeruginosa infection mouse models." (PMID 29228045, 2017).
Arthritis (continued). "Cytokines, such as TNF-α and IL-1β, are often associated with the progression and severity of arthritis." (PMID 28860993, 2017). "Intriguingly, while some inflammatory parameters associated to mBSA/IL-1β-induced arthritis were attenuated by both strategies of tryptase inhibition, the degenerative parameters investigated were not affected." (PMID 28587618, 2017). "This increase of IL-6 associated to mBSA/IL-1β-induced arthritis was dose-dependently reduced by the treatment with APC366, or the previous transduction with phSPAG11B/C." (PMID 28587618, 2017). "Overexpression of IL-1α or IL-1β or deficiency of the soluble IL-1Ra in arthritis models resulted in the development of disease, which is associated with bone and cartilage destruction." (PMID 26634933, 2016). "B6 background IL-38−/− mice developed more severe arthritis than control WT mice, associated with enhanced expression of IL-1β and IL-6 in the ankle joints." (PMID 29124228, 2015). "In an infection model, ISS 4746 and ISS 4749 caused relatively severe arthritis in a higher proportion of mice and induced higher levels of interleukin (IL)-6 and IL-1β in comparison to ISS 3319." (PMID 26452736, 2015). "IL-1α and IL-1β are also expressed in abundance in the synovial membrane, and IL-1Rα-deficient mice develop spontaneous arthritis, mediated in part by amplification of Th17-dependent inflammation." (PMID 26284069, 2015). "Intra-articular injection of SPION during experimental arthritis caused a minor upregulation of TNFα and IL-1β gene expression in the synovium at 2 days after injection, which was on the 5th day of the AIA model." (PMID 25955417, 2015). "In the anti-IL-7R treated TSLPR-/- mice, strongly ameliorated clinical arthritis and immunopathology were associated with decreased levels of IL-17-associated cytokines IL-17 and IL-1β locally and IL-6 systemically." (PMID 26110994, 2015). "This is unlike the situation in most auto-inflammatory disorders, such as familial Mediterranean fever, the cryopyrin-associated periodic syndromes and PAPA (pyogenic arthritis, pyoderma gangrenosum and acne), which are all IL-1β-mediated diseases." (PMID 26091259, 2015). "Inflammatory mediators such as IL-1β have a pivotal role in sustaining both inflammation and cartilage erosion, at least in the pathology associated with arthritis." (PMID 24146983, 2013). "Thus, macrophage training activated the IL‐1β/NAT10/ac4C/FSP1 axis to inhibit ferroptosis of arthritis synovial FLS, indicating a causal link between trained immunity and ferroptotic resistance that contributes to the worsening of inflammatory arthritis." (PMID 41255239, 2025). "Additionally, both CISH and CLU were found upregulated in I) CD4+ TCM and CD4+ TEM and II) CD14+ monocytes, respectively, which are associated with IL-1β-induced and synovial inflammation, and increased levels have been related to psoriasis and arthritis." (PMID 40084238, 2024). "In addition to a TNF‐driven arthritis model, we also evaluated the importance of the microbiome for arthritis development in the IL‐1β‐dependent myeloid‐specific A20‐deficient (A20myel‐KO) mouse model of arthritis." (PMID 37694693, 2023). "Zip8 expression is associated with IL-1β production in monocytes/macrophages in severe arthritis." (PMID 35844594, 2022). "Interestingly, upstream regulator analysis identified TNF (p = 2.34 × 10-36), TGFB1(p = 9.02 × 10-36) and IL-1B (p = 2.39 × 10-32) as known senescence and arthritis associated regulators of DEG miRNAs." (PMID 36213127, 2022). "Thus, as it dampened the expression of proteases, IL1β, and the inflammatory and angiogenic mediators associated with arthritis, the LS-E showed a potential chondroprotective effect by directly acting on chondrocytes." (PMID 36613576, 2022).
Arthritis (continued). "In the current study, we are surprised to find that the expression of SATB2, a critical transcriptional node for osteoblast differentiation, is negatively associated with the levels of TNF-α in OVX-induced bone loss and IL-1β induced arthritis mice by immunohistochemistry." (PMID 29435145, 2018). "Similarly, our laboratory used a serum-induced arthritis mouse model to identify cathepsin B as one of the major proteases in the pro-IL-1β processing in the ROS-deficient Ncf1-/- mice." (PMID 29228045, 2017). "This suggests that additional modulators may collaborate with IL-1β to drive inflammation-associated joint destruction, highlighting the complexity and incomplete understanding of arthritis pathogenesis." (PMID 28122611, 2017). "TNF-α acts synergistically with IL-1β in the production of matrix metalloproteinases, the expression of cell adhesion molecules and the secretion of prostaglandins and these changes result in the joint destruction that is associated with arthritis." (PMID 24940448, 2014). "The 1,407 genes with increased expression in DA and reciprocally decreased expression in DA.F344(Cia5a) congenics included pro-inflammatory cytokines and chemokines implicated in arthritis pathogenesis such as Il1b (5.17-fold on microarray, and 2.46-fold on qPCR), Il18, Mif, Ccl2, Ccl7 and Cxcl13." (PMID 23249408, 2012). "It is also likely that IL-1β-induced cilia elongation will influence other aspects of cilia function including mechanotransduction and hedgehog signaling which has already been linked to arthritis." (PMID 22481441, 2012). "Interestingly, in proteoglycan-induced arthritis, mice deficient in IL-4Rα showed higher IL-1β, IL-6 and MIP1a, whereas levels of IFNγ and autoantibodies were less affected." (PMID 23092393, 2012). "Moreover IL-1β drives pathogenic Th17 cells during spontaneous arthritis in interleukin-1 receptor antagonist (IL-1Ra)-deficient." (PMID 21858022, 2011). "IFN-γ is therefore able to curtail IL-1β induced MMP production by many cell types implicated in perpetuating structural damage in arthritis; cellular responses that could potentially dampen early tissue destruction and joint damage." (PMID 20307272, 2010). "In addition, LPS is known to induce IL-1β and various other cytokines and mediators, such as TNFα and prostaglandin E2, implicated in naturally occurring arthritis." (PMID 19272138, 2009). "In a recent study of adjuvant induced arthritis in a rat model, arthritic changes were associated with raised levels of MMPs, IL-1β and TNF-α in joint tissue; this was ameliorated after TIMP-4 gene therapy in the treated group compared with the untreated control animals." (PMID 19088876, 2008). "Thus, macrophage training aggravates the severity of arthritis, which may be partly associated with the enhancement of IL‐1β signaling and the phenotypic remodeling of FLS in the joint." (PMID 41255239, 2025). "Given that IL-1β is increased in the inflamed joint of the K/BxN-induced arthritis model due to its critical role in inflammatory bone loss, we determined whether parkin is involved in the pathogenesis of inflammatory arthritis and bone density using a K/BxN serum-transfer arthritis mouse model." (PMID 36882866, 2023). "Furthermore, arthritis in KLF2 deficient animals is dependent on IL-1β." (PMID 36466816, 2022). "In addition, IL-1β, IL-6, IL-21, and IL-23 support the differentiation of T helper 17 (Th17) cells, suppress the differentiation of regulatory T cells, and cause inflammation of arthritis." (PMID 32958016, 2020). "IL-1β, is a primary immune response activator that promotes inflammation; it is considered that IL-1RN receptors, which recognize this cytokine, play an important role in the systemic inflammation in arthritis development and kidney damage associated to SLE type autoimmunity." (PMID 28587079, 2017). "However, it is not yet clear whether circulating EPCs are associated with the regulation and mechanistic function of IL-1β during arthritis." (PMID 26811540, 2016).
Arthritis (continued). "Indeed, during arthritis-induced sterile inflammation, caspase-1-independent processing of IL-1β leads to disease-associated inflammation as a result of neutrophil recruitment and proteinase 3, while P. aeruginosa infections of the cornea require neutrophil elastase." (PMID 25198773, 2014). "Also, the effect of HLM on IL-1β-induced NO production are interesting as inhibition of NO has been associated with the reduced pain, inflammation, proteoglycan loss in human OA patients and in animal models of arthritis." (PMID 21854562, 2011). "Furthermore, IL-1β is implicated in multiple pathologies leading to tissue damage such as arthritis, transplant rejection, Alzheimer's, Crohn's disease, systemic lupus erythematosus, septic shock, tumorigenesis and metastasis, lymphoprolipherative disorders and pulmonary fibrosis." (PMID 18286207, 2008). "Administration of 26 mg/kg of the extract had maximally reduced the symptoms of arthritis, improved protective mediators (IL-4), decreased inflammatory cytokines (IL-1β, IL-6, IL-17, and IFN-γ), and restored joint structure." (PMID 41495193, 2026). "Studies in mice have also shown that BBR can improve the clinical symptoms of various types of arthritis by downregulating the expression levels of inflammatory factors, such as IL-1β, IL-6, and TNF-α." (PMID 40829428, 2025). "When comparing healthy rams to those with arthritis, the expression levels of the following genes were noticeably higher: IL-1α, IL-1β, IL-6, IL-10, TNFα, NCF4, NFKB, TMED, FCAMR, iNOS and COX18." (PMID 40005882, 2025). "The development of arthritis was accelerated and characterized by increased circulating levels of IL-1β and reduced IL-5." (PMID 40370470, 2025). "It has been reported that AB4 reduced the level of IL-1β and suppressed ferroptosis-mediated inflammation to alleviate arthritis pain." (PMID 39877642, 2025). "AD-MSCs treatment has consistently been shown to reduce the levels of IL-1β and TNFα, key cytokines involved in the inflammatory response and the development of structural bone and cartilage damage in arthritis." (PMID 40493163, 2025). "Along these lines, the P2X4 receptor antisense oligonucleotides reduced synovial inflammation in the collagen-induced mouse model of arthritis by modulating the serum levels of IL-1β, TNF-α, IL-6, and IL-17." (PMID 41002432, 2025). "Reference mapping showed that the majority of ICI-arthritis myeloid cells mapped onto four RA myeloid clusters: IL1B + FCN1 + HBEGF+, STAT1+ CXCL10+, SPP1+, and MERTK+ HBEGF+ clusters." (PMID 40662950, 2025). "IL-1β-expressing macrophages have been implicated in the pathogenesis of RA, ICI-arthritis, and pancreatic cancer, but the mechanisms that induce these cells and the extent to which they contribute to arthritic phenotypes are not known." (PMID 40662950, 2025). "A total of 6 mg/kg/d for 22 days improved foot-plantar swelling and arthritis scores in RA rats and regulated the balance of pro-inflammatory factors, such as IL-1β, IL-6, and IL-17A, and anti-inflammatory factors, such as IL-4 and IL-10." (PMID 40864815, 2025). "We further showed that the mechanism of reversal of arthritis was, in part, due to rFc-μTP-L309C able to inhibit neutrophil infiltration into the joints as well as inhibition of IL-1β production." (PMID 40648884, 2025). "During induction, both Mid1 and IL-1β expression levels remain relatively low, with an increase in the early phase of arthritis, and persisting throughout the acute phase." (PMID 40443734, 2025). "IL-1β, IL-6, IL-8, and TNF-α are small proteins associated with inflammation secondary to arthritis or disk disorders and have an important role in the onset and progression of TMDs." (PMID 40142185, 2025). "It has been noted that IL-1β, one of these cytokines, has important roles in arthritis pathogenesis through the regulation of inflammatory reactions, in addition to having direct catabolic effects on cartilage and SF." (PMID 40543258, 2025).
Arthritis (continued). "In a collagen‐induced arthritis model, trained macrophages intensify disease severity and confer ferroptosis resistance in synovial cells via IL‐1β/NAT10‐mediated FSP1 mRNA modification." (PMID 41255239, 2025). "Therapeutic effects were assessed via arthritis index, paw swelling, and serum cytokines (IL-1β, IL-6, IL-17A)." (PMID 40864815, 2025). "Among the IL-1 family, IL-1β, a prominent product of myeloid cells, has been extensively studied and demonstrated to have elevated levels in arthritis." (PMID 40406113, 2025). "QRHXD and MTX significantly reduced toe swelling and arthritis, decreased inflammatory factors such as IL-1β, IL-6, IL-17, and TNF-α, and increased the anti-inflammatory factor IL-10." (PMID 40124380, 2025). "The rams with arthritis showed significantly greater levels of gene expression for the genes IL-1α, IL-1β, IL-6, IL-10, TNFα, NCF4, NFKB, TMED, FCAMR, iNOS and COX18 than did the healthy rams." (PMID 40005882, 2025). "Arthritis symptoms were improved in mice with collagen-induced arthritis when administered daptomycin, and the serum levels of IL-1β, TNF-α, and IL-6 were decreased." (PMID 41226564, 2025). "The introduction of monoclonal antibody that targets IL-1β has achieved success in the treatment of chronic immune-inflammatory diseases such as psoriasis, arthritis, or type 2 diabetes." (PMID 40066372, 2025). "Cytokines such as TNF-α, IL-1β, and IL-6 induce joint inflammation and upregulate the production of MMPs (1, 2, 3, 7, 8, 9, and 13) through inflammatory signaling." (PMID 40427394, 2025). "The myeloid compartment includes IL-1ß-hi monocyte and macrophage subsets, and ICI-arthritis synovial fluid contains elevated levels of IL-1β, IL-6, IFN-γ, and IL-17A." (PMID 40662950, 2025). "Gene expression intensities were much higher in the arthritis-affected rams than in the healthy ones for the genes IL-1α, IL-1β, IL-6, IL-10, TNFα, NCF4, NFKB, TMED, FCAMR, iNOS and COX18." (PMID 40005882, 2025). "In this study, intraarticular injection of SAA markedly propelled progression of IL-1β–induced arthritis." (PMID 38426494, 2024). "The IDM DMN treatment effectively reduced arthritis severity, resulting in decreased paw swelling, arthritis index, spleen hyperplasia, and serum IL-1β and TNF-α levels." (PMID 39771485, 2024). "Inflammatory mediators are known to play a pivotal part in arthritis pathogenesis, characterized by chronic inflammation marked by increased pro‐inflammatory cytokine levels, including interleukin‐1β (IL‐1β) and tumor necrosis factor‐α." (PMID 39508645, 2024). "Most strikingly, on day 7, hepatic (extraarticular) overexpression of mSaa1 caused an increase in the pathology of the affected joints, i.e., at remote sites, in mice with IL-1β–induced arthritis." (PMID 38426494, 2024). "IL‐1β plays a critical role in the development of arthritis as it initiates an inflammatory response and promotes the activation and proliferation of inflammatory cells in joints." (PMID 39554315, 2024). "In a mouse model of RA, IFNλ2 treatment reversed arthritis by suppressing IL-1β and restricting neutrophil recruitment to inflammatory sites." (PMID 39399119, 2024). "We demonstrated that an intra-articular injection of recombinant ORM2 into affected joints aggravated the severity of IL-1β-induced arthritis in mice, accompanied by a marked increase in macrophage infiltration." (PMID 38556552, 2024). "In mice with mBSA+IL-1β–induced arthritis, the signal was also increased exclusively in the liver after viral transfer similarly in mice with Ad-mSaa1 versus those with empty vector only." (PMID 38426494, 2024). "Genetic ablation of Ncoa6 substantially attenuated the severity of FA-induced ATN and MSU crystal-induced arthritis in mice and decreased IL-1β and active caspase-1 levels." (PMID 38195836, 2024).